SCD (stearoyl-CoA desaturase)
Diseases named in the same sentence as SCD in open-access papers (continued):
Sharing a sentence is not in itself a finding about the gene and the disease.
cancer (continued). "SCD deletion and hypermethylation in PTEN-deleted cancers, however paradoxical, are inadvertent events in the cancer genome." (PMID 33568479, 2021). "Stearoyl-CoA desaturase (SCD)-1, one of the important lipogenic enzymes, has recently been indicated as a potential pharmaceutical target in cancer therapy." (PMID 32630668, 2020). "siRNAs specific for SCD and CDH3, as well as plasmids harboring full-length human SCD and CDH3 sequences, were designed and transfected into cancer cells." (PMID 32873775, 2020). "This breakthrough discovery sheds new light on the idea of targeting desaturation pathways in cancer cells, and suggests that only combined inhibition of SCD and FADS2 can become a fully effective way of treating certain types of cancer." (PMID 31284458, 2019). "It was shown that, in contrast to SCD-dependent cancer cells, the level of the unusual MUFA sapienate (cis-6-C16:1) was elevated in partially SCD-dependent and SCD-independent cancer cells, and increased upon administration of the SCD inhibitor." (PMID 31284458, 2019). "We analyzed the expression of five major DNFA enzymes SCD, FASN, ACLY, ACSS2 and ACACA using RNA-Seq data from 30 diverse cancer types in The Cancer Genome Atlas (TCGA)." (PMID 31316083, 2019). "ACSL4 has been previously reported overexpressed in malignant tumors, and together with ACSL1 and SCD form a metabolic axis involved in CRC progression." (PMID 31339921, 2019). "Other enzymes within the FA biosynthesis pathway have also been targeted experimentally and were shown to limit the growth and proliferation of cancer cells; such enzymes include ACC and SCD." (PMID 24203995, 2013). "SCD, which mediates the formation of monounsaturated fatty acids (MUFA) and is related to ferroptosis resistance, showed expression levels of 0.7122, 0.2897, and 0.1811 in primary cancer, CRPC, and normal samples, respectively." (PMID 39988626, 2025). "Both studies underscore the role of desaturases in tumor metabolism, suggesting that SCD-mediated MUFA biosynthesis may have distinct functions in various cancers through genetic and epigenetic regulation, potentially influencing cancer progression." (PMID 40430008, 2025). "Furthermore, overexpression of stearoyl-CoA desaturase 1 (SCD1), a key desaturase in the synthesis of MUFA, promotes HCC tumor growth and empowers cancer cells with resistance to sorafenib treatment." (PMID 38698462, 2024). "The expression of various lipid synthases is elevated in cancer cells, including sterol regulatory element binding proteins (SREBPs), ATP-citrate lyase (ACLY), acetyl-CoA carboxylase (ACC), fatty acid synthase (FASN), and stearoyl-CoA desaturase 1 (SCD1)." (PMID 38994204, 2024). "Moreover, SCD was also positively correlated with epithelial-mesenchymal transition (EMT) and hypoxia, suggesting that SCD is a key factor in promoting cancer malignancy." (PMID 39351232, 2024). "Interestingly, analysis of the Depmap dataset shows that SCD dependency inversely correlates with the expression levels of both FASN and ACACA (ACC) across all cancer cells lines and particularly AML ones." (PMID 39187579, 2024). "Moreover, recent evidence showed that KRAS mutant cancer cells are also able to desaturate palmitate to sapienate via fatty acid desaturase 2 (FADS2), an event that confers additional independence to SCD-mediated FA desaturation." (PMID 36675307, 2023). "In addition to dietary intake, the expression of desaturation enzymes also influences the amount of SFAs in membrane lipids and in several cancer types, downregulation of stearoyl-CoA desaturase (SCD) 5 has been observed, while SCD1 is often overexpressed." (PMID 36830818, 2023).
cancer (continued). "As the limiting step in MUFA synthesis, SCD activity (and its modulation using pharmacological inhibitors or by over/under-expression) provides insights into the impact of endogenously synthesized MUFA on cancer." (PMID 37373069, 2023). "However, to maintain proliferation, cancer cells also need to convert SFAs into MUFAs to reduce the intrinsic cytotoxicity of SFA and inhibition of SCD enzymes has been shown to worsen palmitic acid cytotoxicity." (PMID 36830818, 2023). "Here, we applied the OzFAD pipeline to characterize the total fatty acid profiles of three cancer cell lines (i.e., MCF7, LNCaP and LNCaP_SCD1i; SCD-1 inhibition: A939572) and investigate the effect of enzyme expression and inhibition of stearyl-CoA desaturase-1 (SCD-1/Δ9-desaturase)." (PMID 37402773, 2023). "Meanwhile, these genes regulated by SREBP-1, including ACLY, ACC, FASN, and SCD, are highly expressed in cancer tissues compared to adjacent non-tumor tissues, which play essential roles in the growth, metastasis, and survival of various cancers." (PMID 35912181, 2022). "Alternatively, SCD‐1, an enzyme involved in converting saturated fatty acids to monounsaturated fatty acids (MUFA) with double bonds at the Δ9 position, has been shown to be overexpressed in cancer." (PMID 36028991, 2022). "Previous study showed SR9009 could induce the apoptosis of cancer cells by suppressing autophagy and de novo lipogenesis through repressing fatty acid synthase (FAS) and stearoyl‐CoA desaturase 1 (SCD1)." (PMID 34587364, 2021). "Cancer cells develop capable de novo FAS machinery with an increase in the activity of key lipogenic enzymes such as adenosine triphosphate (ATP)-citrate lyase (ACLY), acetyl-CoA carboxylase (ACC), CoA carboxylase (ACACA), fatty acid synthase (FASN), and SCD." (PMID 33364199, 2020). "In fact, lipid desaturation, mainly via the enzyme stearoyl-CoA desaturase (SCD-1), plays essential functions controlling self-renewal and tumorigenicity in different cancer models, possibly through the activation of stemness-related pathways, such as Wnt signaling." (PMID 30967773, 2019). "Of note, a universal feature of cancer is the enhanced lipid biosynthesis, which is reflected in the activation of several key lipogenic factors, including ACLY, ACACA, FASN, and SCD, as well as the increased activity of the SREBP family of transcription factors." (PMID 30949448, 2019). "We found that high expression of SCD, FASN and ACACA significantly correlates with poor prognosis in all cancers considered collectively." (PMID 31316083, 2019). "Therefore, we propose this system to get insight into cancer progression mechanisms in regards to fatty acid metabolism and therefore, to assay ACSL/SCD protumorigenic axis action in CRC." (PMID 31339921, 2019). "The significant roles of SCD and FASN in cancer development have been well established in the past." (PMID 31083642, 2019). "Inhibition of both desaturases, SCD and FADS2, resulted in reduced cancer growth in vivo, suggesting that targeting of multiple pathways may be needed in order to effectively impair cancer metabolic plasticity." (PMID 31922096, 2019). "Furthermore, stearoyl-CoA desaturase (SCD), an enzyme involved in fatty acid biosynthesis and a target gene of SREBP1, is overexpressed in several human cancers." (PMID 29991569, 2018). "We found that silencing of SCD reduced proliferation in almost all cancer cells lines studied without affecting the viability of non-malignant epithelial cell lines derived from the same tissues." (PMID 27042297, 2016). "The fact that fibroblasts were completely unresponsive to the cytostatic effect of the SCD inhibitor suggests that non-cancer cells have a smaller requirement for endogenously produced MUFA than cancer cells." (PMID 20613975, 2010).
cancer (continued). "These alterations resulting from SCD blockade were fully reversed by either oleic (18:1n-9), palmitoleic acid (16:1n-7) or cis-vaccenic acid (18:1n-7) demonstrating that cis-MUFA are key molecules for cancer cell proliferation." (PMID 20613975, 2010). "We have previously shown that a stable knockdown of stearoyl-CoA desaturase 1 (SCD1), the main Δ9-desaturase that converts SFA into MUFA, in cancer cells decreases the rate of lipogenesis, reduces proliferation and in vitro invasiveness, and dramatically impairs tumor formation and growth." (PMID 19710915, 2009). "The downregulation of the key adipogenic factors (C/EBPβ, C/EBPα, PPARγ and SREBP-1c) together with the repression of lipogenic factors (ACC, FAS, SCD-1, GPAT and Glut-4) suggests that impairment in the formation and lipid storing capacity of adipose tissue occurs in cancer cachexia." (PMID 17047651, 2006). "Repression of SREBP-1c and its targets (ACC, FAS, SCD-1 and GPAT) in the pathway of fatty acid and triglyceride synthesis may indicate an inhibition of de novo lipogenesis in adipose tissue in cancer cachexia." (PMID 17047651, 2006). "FADS2 converts them into arachidonic acid and, interestingly, palmitate can compete with linoleic and alpha-linoleic acids in this reaction, which could explain the ability of FADS2 to compensate for the lack of SCD activity in cancer cells." (PMID 40404984, 2025). "However, not all cancers exhibit sensitivity to SCD inhibition, as some tumor cells rely on compensatory desaturation pathways that utilize FADS2 to generate sapienate from palmitate esters." (PMID 41421797, 2025). "A recent publication underscored critical importance of desaturation for cancer cells that exploits a metabolic rewiring process and engages an alternative fatty acid desaturation pathway using the fatty acid desaturase 2 (FADS2) enzyme instead of the conventional desaturation by SCD." (PMID 39337514, 2024). "Consequently, several enzymes involved in LD formation or breakdown, such as ACC, fatty acid synthase (FASN), 3-hydroxy-3-methylglutaryl monoacyl-CoA reductase (HMGCR), and stearoyl-CoA desaturase (SCD), have been identified as potential therapeutic targets in cancer treatment." (PMID 38916672, 2024). "Moreover, probably by causing the accumulation of saturated fatty acids, pharmacological inhibition of SCD slows tumor growth down in preclinical cancer models without affecting overall body weight." (PMID 35006438, 2021). "Given their effect on the fundamental mechanism of lipid saturation this may not be surprising, and, in fact, SCD inhibition is being investigated as a strategy of preventing cancer cell growth." (PMID 32707907, 2020). "Therefore, inhibition of exogeneous fatty acid uptake by targeting CD36 may synergize with inhibition of desaturation by targeting SCD (e.g., via small molecules CAY-10566 and TOFA39,40) in killing hypoxic cancer cells." (PMID 32103057, 2020). "Activation of the stearoyl-CoA desaturase (SCD) enzyme by the HCV replication machinery and in cancer cells may lead to an increased production of monounsaturated fatty acids concomitant to decreased levels of saturated fatty acids in viral-related CLD and HCC patients." (PMID 33396945, 2020). "Cancer cells activate de novo lipogenesis by upregulation of key enzymes in lipid metabolism, some of which, such as AcetylCo-A Lyase (ACLY), AcetylCo-A Carboxylase (ACC) and Stearoyl-CoA desaturase-1 (SCD), are targets of pharmacological inhibitors to decrease cancer proliferation." (PMID 30881374, 2019).
cancer (continued). "De novo synthesis of FA is activated in cancer cell, which is catalyzed by ATP citrate lyase (ACLY), acetyl-CoA carboxylase (ACC) and fatty acid synthase (FASN), then converted to monounsaturated FA (MUFA) to generate triacylglycerol (TAG), the composition of LDs, by stearoyl-CoA desaturase (SCD)." (PMID 31777589, 2019). "Indeed, inhibition of SCD has been shown to induce CHOP expression and apoptosis in cancer cells." (PMID 24280005, 2013). "Stearoyl-CoA desaturase-1 (SCD1) is a microsomal enzyme that regulates the conversion of SFA (palmitic [16∶0] and stearic acid [18∶0]) into MUFA (palmitoleic [16∶1] and oleic acid [18∶1], respectively) and is suggested to play an important role in cancer progression." (PMID 23613812, 2013). "However, a distinctive aspect of this lipogenic transformation is that cancer cells also contain a large pool of monounsaturated fatty acids (MUFA), which are largely generated from SFA by the action of stearoyl-CoA desaturases (SCD)." (PMID 24212819, 2011). "Studies showing that abnormally high levels of SCD1, the best characterized SCD isoform, are commonly found in oncogene-transformed cells and several types of cancer cells provided initial evidence that this enzyme may be functionally associated with the onset and progression of cancer." (PMID 24212819, 2011). "Through pan-cancer analysis, we found that SCD mainly has differences in expression and prognosis in four kinds of tumors (BLCA, CESC, KICH, LGG), and the expression of SCD in LGG is the highest in all tumors, confirming that SCD gene may play a role mainly in head disease and reproductive system." (PMID 38625951, 2024). "However, SCD activity is not limited in its impact to cancer cell biology." (PMID 37373069, 2023). "The overall view is that SCD plays a role in mitogenic and stress-related signal transduction pathways, but it remains to be determined whether lipid factors, such as altered saturated/MUFA profiles, mediate the pleiotropic activities of SCD in cancer cell biology (see review)." (PMID 33413672, 2021). "SCD inhibition has been targeted at epithelial ovarian cancer (EOC) to significantly reduce the proliferation of EOC cells and patient-derived organoids and induced apoptotic cell death, while not affecting the non-cancer cells." (PMID 39966220, 2025).
tumor (405 papers, 2006 to 2026). "SCD upregulation was observed in 54.4% of 1968 HCC tumours, and high SCD expression was associated with shorter OS." (PMID 41383134, 2025). "Further analyses identified significant associations between SCD expression and various immune markers in tumor microenvironment." (PMID 39351232, 2024). "SREBP is a transcription factor that promotes DNL by upregulating key enzymes such as ACLY, FASN, and SCD, which are closely linked to tumor proliferation, apoptosis, and invasion." (PMID 37700339, 2023). "We observed the expression of ABCA1 and SCD mainly in tumor-associated macrophages (cluster 2), while HMGCR was mainly expressed in DCs." (PMID 36792589, 2023). "We previously associated the expression of cellular hypoxia markers with SCD-1 overexpression in a large number of tumor samples (n = 24)." (PMID 34199164, 2021). "Notably, SCD-1 converts SFAs into unsaturated FAs to maintain their equilibrium, causing the tumor cells to survive." (PMID 39920872, 2025). "Moreover, the production of unsaturated FAs caused by increased SCD activity enhances tumor cell resistance." (PMID 38184562, 2024). "Notably, SCD emerged as a pivotal enzyme in lipid metabolism, with its expression intricately linked to malignant transformation, tumor proliferation, and OS." (PMID 39075554, 2024). "SCD upregulation was also linked to tumor aggressiveness and poorer prognosis in ccRCC." (PMID 36980176, 2023). "SCD upregulation has been associated with tumor aggressiveness and progression." (PMID 34503180, 2021). "The IDH1 mutation causes an increase in SCD activity in the tumor." (PMID 32392704, 2020). "SCD expression is also increased in neoplasms and is associated with worse prognosis for patients." (PMID 32392704, 2020). "The results of in vitro and in vivo experiments showed that acidic environments caused SCD NPs to degrade and greatly increase oxidative stress at the tumor site and caused damage to cellular proteins and DNA, leading to apoptosis and the significant inhibition of tumor growth." (PMID 40574008, 2025). "Likewise, Immunohistochemistry (IHC) for SCD expression on human lung tissue array revealed that the mean intensity score of SCD staining was higher in adenocarcinoma compared with normal lung tissue, and was positively associated with increase of tumor grade and clinical stage." (PMID 36514170, 2022). "Importantly, the increased tumor expression of SCD is associated with worse prognosis." (PMID 32392704, 2020). "Mechanisms by which the Stearoyl-CoA desaturase (SCD1) inhibitor aramchol kills tumor cells have recently been described, demonstrating that enhanced signaling through the AMPK played a key role in the processes regulating cell death." (PMID 41954991, 2026). "Fatty acid synthase (FASN) is a rate-limiting enzyme in FA synthesis, while stearoyl-CoA desaturase-1 (SCD1) converts saturated fatty acids to monounsaturated fatty acids (MUFAs), promoting membrane fluidity and tumour survival." (PMID 41154605, 2025). "Lipid levels in the plasma and tumors of mice decrease after caloric restriction (CR), and CR causes an imbalance between unsaturated and saturated fatty acids by compromising the activity of tumor SCD, thereby slowing tumor growth." (PMID 40002387, 2025). "Lipid-targeting (e.g., FASN, Acetyl-CoA carboxylase (ACC), Stearoyl-CoA desaturase 1 (SCD1) inhibitors) acts as a metabolic trap: impairing tumour-lipid supply, altering membrane composition and increasing vulnerability to immune attack." (PMID 41394868, 2025). "Lower levels of oleic acid and total MUFAs levels indicated this phenomenon in tumor adjacent tissue compared to healthy tissue, although higher gene expression of stearoyl-CoA desaturase-1 (SCD1) was detected in cPTC than in fPTC tissue (p = 0.015)." (PMID 39145825, 2025).